ELMOD2 (ELMO domain containing 2)
Description:
Acts as a GTPase-activating protein (GAP) toward guanine nucleotide exchange factors like ARL2, ARL3, ARF1 and ARF6, but not for GTPases outside the Arf family. Regulates IFN-related antiviral responses.
Synonyms: MGC10084; 9830169G11Rik
Tractability: PROTAC: ubiquitination databases record sites on it; its protein half-life has been measured.
Gene: Protein-coding gene on chromosome 4 (140,524,164 to 140,553,775, forward strand). Ensembl gene ENSG00000179387.
Subcellular location (Human Protein Atlas): Actin filaments; Nuclear bodies; Cytosol; Nucleoplasm
Gene Ontology:
Molecular function: GTPase activator activity
Biological process: regulation of defense response to virus
Cellular component: membrane
Genetic constraint (gnomAD): Loss-of-function variants: 20 observed, 32.98 expected, observed/expected ratio (o/e) 0.61, 90% interval 0.43 to 0.88. The upper end of that interval is the gene's LOEUF score, 0.88, which puts it in group 3 of 6, group 1 being the genes least tolerant of losing a copy. Missense variants: 299 observed, 316.36 expected, observed/expected ratio (o/e) 0.95, 90% interval 0.86 to 1.04. Synonymous variants: 99 observed, 101.8 expected, observed/expected ratio (o/e) 0.97, 90% interval 0.83 to 1.15.
Gene-disease validity (ClinGen):
ClinGen rates the evidence that ELMOD2 causes each of these diseases.
idiopathic pulmonary fibrosis (inheritance undetermined): No Known Disease Relationship.
Homologues: Orthologues: chimpanzee ELMOD2 (99% identical), macaque ELMOD2 (99% identical), rabbit ELMOD2 (95% identical), dog ELMOD2 (94% identical), pig ELMOD2 (94% identical), guinea pig ELMOD2 (92% identical), mouse Elmod2 (87% identical), rat Elmod2 (86% identical), rat Elmod2 (79% identical), tropical clawed frog elmod2 (67% identical), zebrafish elmod2 (61% identical), Drosophila melanogaster CG10068 (43% identical). Paralogues in human: ELMOD1 (54% identical), ELMO3 (20% identical), ELMO1 (19% identical), ELMOD3 (19% identical), ELMO2 (18% identical).
Diseases named in the same sentence as ELMOD2 in open-access papers:
ELMOD2 is named in the same sentence as 8 diseases in open-access papers, as found by Europe PMC text mining. Sharing a sentence is not in itself a finding about the gene and the disease. The quoted sentences say what the papers report.
lung fibrosis (4 papers, 2015 to 2022). "In more detail, HLA-DPB1 is a known COPD gene related to disease severity, SERPINA6 was associated with emphysema, a deletion in ADORA2B was shown to be associated with a decrease in lung fibrosis and pulmonary hypertension, and ELMOD2 is a candidate gene for familial idiopathic pulmonary fibrosis." (PMID 30845926, 2019). "Hence, hypofunctional TLR3 mutations and ELMOD2 gene deficiency in IPF may contribute to progressive lung fibrosis via a decreased type I IFN response, which suggests that induction of MX1 expression in IPF is not mediated by type I IFN." (PMID 35391716, 2022). "There are many candidate genes implicated in pulmonary fibrosis, such as IGF-I, IGFBPs, ELMOD2, TERT, TERC, SFTPC, SFTPA2), and MUC5B." (PMID 26447616, 2015).
Hepatic steatosis (1 paper, 2025). Steatosis is a term used to denote lipid accumulation within hepatocytes. "Lower ELMOD2 levels may facilitate greater recruitment of ATGL to LDs, thereby enhancing TG breakdown and reducing hepatic steatosis through increased ATGL activity." (PMID 39969435, 2025).
steatosis (1 paper, 2025). Increased lipid within the cytoplasm of cells. "Collectively, these results suggest that hepatic Faf2 knockdown may ameliorate alcohol-induced steatosis by enhancing lipolytic activity through increased ATGL transport to LDs and its activation by CGI-58 and ELMOD2." (PMID 39969435, 2025).
respiratory diseases (1 paper, 2020). "ELMOD2 was associated with activity variability during wake, sleep duration, sleep end and daily rhythmicity and its function may be related to respiratory diseases." (PMID 33075057, 2020).
ELMOD2 also shares sentences with these, for which no sentence is quoted: emphysema (1 paper); familial idiopathic pulmonary fibrosis (1); hypothyroidism (1); pulmonary hypertension (1).